BRCA1 (BRCA1 DNA repair associated)
Diseases named in the same sentence as BRCA1 in open-access papers (continued):
Sharing a sentence is not in itself a finding about the gene and the disease.
cancer (continued). "As such, they are not suited for integration in the clinical management of patients suffering from progressing cancer, in whom a variant of unknown significance (VUS) in a homologous recombination gene, such as BRCA1 or BRCA2, is discovered." (PMID 34206535, 2021). "As these changes are known to cause cancer, radiation-induced carcinogenesis may occur in BRCA mutation carriers, as BRCA1/2 is involved in double-strand break repair." (PMID 32862296, 2021). "Therefore, inability to repair complex DNA damage, such as mutations in BRCA1 and BRCA2 tumour suppressor genes, can lead to genomic instability and predisposition to cancers." (PMID 34572747, 2021). "These OC or BC cases were selected based on their family history of OC or BC, or regardless of cancer family history (sporadic cases), where BRCA1 and BRCA2 pathogenic variant carrier status was known." (PMID 34861889, 2021). "Only a small fraction (~5%) of cancers have hereditary defects in BRCA1 or BRCA2." (PMID 34481156, 2021). "Patients with first cancer diagnosis and survivors of some cancers may be screened for genetic risk factors such as MMR and BRCA1/BRCA2 mutations." (PMID 34556087, 2021). "BRCA1 or BRCA2 germline mutations predispose to breast, ovarian and other cancers." (PMID 34389725, 2021). "Thus, treatment strategies that eliminate BRCA1/2-mutant tumors are likely to have a substantial impact on various cancer types and reducing the global cancer burden." (PMID 35008272, 2021). "Thus, our work demonstrates that β-catenin toxicity in cancer cells with compromised BRCA1/2 function is driven by transcriptional alterations that cause aberrant replication and inflict DNA damage." (PMID 34389725, 2021). "It is difficult to make a direct comparison between BRCA2-mutated and BRCA1-mutated tumors as the distribution of these mutations differs across cancer types and the correlation between the BRCA1 mutation status and OS was not controlled for tumor type." (PMID 34067105, 2021). "Given the functional interaction of PALB2 with BRCA1 and BRCA2, and the phenotypic similarities of the associated cancers presented within and by others, it is likely these agents will also be of utility in the treatment of PALB2 deficient cancers." (PMID 34113003, 2021). "The purpose was to explore if the capacity to activate a cancer stem cell network might be a clue to the ability of BRCA1/2-proficient cells to evade PARPi treatment." (PMID 34069138, 2021). "BRCA1 and BRCA2 have been established as high risk cancer predisposing genes, as heterozygous carriers of pathogenic variants (PVs; all variants in this review are germline unless otherwise stated) have absolute risks greater than 60% for BC and 13–58% for OC, depending on the gene involved." (PMID 34298626, 2021). "For example, restoration of BRCA1/BRCA2 activity due to reversion mutations, promoter demethylation, or the amplification of the mutant BRCA2 allele have all been associated with cancer resistance to PARPi." (PMID 33809714, 2021). "Understanding cancer cell behavior and associated tissue alterations that arise as a result of loss of BRCA1 function may help improve current therapeutic strategies employed to treat BRCA1 mutant cancers." (PMID 35008272, 2021). "Whether the lack of toxicity in MCF10A and RPE1 cells can solely be attributed to the presence of BRCA1 or whether it can also be partially explained by an overall decreased cellular uptake rate in normal versus cancer cells requires further investigation." (PMID 33608267, 2021). "Moreover, loss of BRCA1 RING domain function appears insufficient to fully sensitize cells to PARP inhibition, while still predisposing to cancer development." (PMID 34456966, 2021).
cancer (continued). "In the future, we may take this challenge and try to analyze these more complex forms of BRCA1 VUSs, so as to acquire more insights between BRCA1 VUSs and cancers." (PMID 33937409, 2021). "In this review, we will discuss the role of BRCA1 in genomic integrity and cancer metastasis, specifically focusing on BRCA1 function in epithelial to mesenchymal transition (EMT), cell adhesion, cell invasion, tumor neovascularization, and tumor microenvironment." (PMID 35008272, 2021). "Inherited BRCA1 and BRCA2 mutations are associated with increased lifetime risks of breast and ovarian cancers by 45–75% and 18–40%, respectively, as well as other cancers like pancreatic and prostate cancers." (PMID 34206661, 2021). "BRCA1-mutant cancer cell line HCC-1937 has a constitutively high c-Abl kinase activity." (PMID 34616682, 2021). "In addition to ICIs, tumors with deleterious DDR gene mutations, especially BRCA1/2 genes, were also associated with higher sensitivities to poly (ADP ribose) polymerase inhibitors (PARPi) in pan-cancers." (PMID 33588785, 2021). "Awareness should be implemented, also among medical professionals, regarding all the mentioned reproductive health-specific issues of BRCA1/2 pathogenic variant carriers, from fertility to PGT to pregnancy after cancer, including indications to contraception and hormonal menopause therapy." (PMID 34503502, 2021). "Using large breast cancer datasets, researchers were able to show that, unsurprisingly, BRCA-1 and BRCA-2 mutated cancers did have an increased proportion of homologous recombination deficiency (HRD) genetic signatures and overall mutational load compared to BRCA proficient cancers." (PMID 34944679, 2021). "Although not a direct drug target, cancer patients with BRCA1 mutation or homologous recombination deficiency (HRD) exhibit a good response to the treatment with PARP inhibitors, such as olaparib." (PMID 34068585, 2021). "Representing a complex and heterogeneous type of cancer, its occurrence is attributed by both genetic (gene mutations, e.g., BRCA1, BRCA2) and non-genetic (race, ethnicity, etc.)risk factors." (PMID 34199484, 2021). "In contrast to platinum agents, microtubule-inhibiting agents such as taxanes are significantly less effective in BRCA1/2-mutated cancers, though the precise mechanism of resistance has not yet been identified." (PMID 34070674, 2021). "Diagnostic tests involve sequencing of BRCA1 and BRCA2 (and perhaps other genes, e.g. PALB2), aiming to detect any variant present that might increase cancer risk." (PMID 34649841, 2021). "A more complete understanding of these multivalent interactions may provide new avenues for therapeutic intervention in cancer types driven by BRCA1 dysfunction." (PMID 34659365, 2021). "However, further investigations are needed to define the mechanistic of BRCA1/2 gene status on G4 binder immune gene activation in cancer cells." (PMID 34139015, 2021). "However, the benefit of prophylaxis mastectomy has only been proven in some specific genetic-related cancer types, such as BRCA1 and BRCA2, in reducing contralateral cancer risk; the benefit for survival remains under debate." (PMID 34209279, 2021). "Cancer in less than 35-year-olds was detected only in BRCA1." (PMID 34719391, 2021).
cancer (continued). "In addition to impairing DNA repair, PARP1/PARP2 inhibitors—which are in clinical use against a growing list of cancers—trap the abundant PARP1 protein on DNA breaks, which has genotoxic cytotoxic consequences, especially in BRCA1- or BRCA2-deficient cancers." (PMID 34210965, 2021). "By characterizing the key factors that are altered in BRCA1-haploinsufficient stromal cells, it might be possible to identify therapeutic strategies to prevent or treat BRCA-associated cancers." (PMID 33513753, 2021). "Using a multivariate regression model, corrected for age and genetic ancestry represented by principal components, we found 12 positive correlations between the HRD score and germline variants in five (i.e., BRCA1, BRCA2, PABL2, ATM, ATR) genes across cancer types." (PMID 34572800, 2021). "Similarly to BRCA1 or BRCA2 gene mutations, oncogene activation represents an early driver of tumourigenesis, providing cancer cells with selective growth advantage." (PMID 34389725, 2021). "Preclinical and clinical evidence have demonstrated that PARPi also affect cancer cells with other DNA repair mechanism defects (i.e., cells not harboring BRCA1/2 mutations)." (PMID 34504648, 2021). "As for HCC-1937 and MDA-MB-436, M2 and M3 were equipotent (p ≥ 0.1297) suggesting that the small difference in spacer length (two CH2-groups) between M2 and M3 had no major effect on cancer cell viability in these BRCA1-mutated cells." (PMID 34356606, 2021). "Eight hundred seventy-four patients with BC or OC, enrolled from October 2016 to December 2020 at our institute, who met the criteria concerning personal and family history of cancer recommended by the AIOM national guidelines, were genetically tested for germline BRCA1/2 variants." (PMID 34178674, 2021). "A study of BRCA1/2 alterations across cancer types reported significantly higher measures of a composite HRRd score in tumors with heterozygous loss of BRCA1/2 compared with tumors without alterations." (PMID 34877933, 2021). "Studies have not investigated the similarities of this trend among BRCA1/2 -positive women who are considered high risk for these cancers." (PMID 34401875, 2021). "A few reports suggested a correlation between prognosis and the presence or absence of LOH in cancers of germline BRCA1/2 mutation carriers." (PMID 32862296, 2021). "Five pathogenic variants (two in BRCA1 and three in BRCA2) were present only in general population with five carriers, and three BRCA2 pathogenic variants were present in both general population and the cancer cohort with six carriers." (PMID 34235180, 2021). "Cancers without BRCA1/2 loss but with accumulation of similar genomic footprints displayed increased sensitivity to DNA-damaging agents." (PMID 34869593, 2021). "ASA-A, ASA-B and POPA brought about a considerably higher increase of the PARP2/ACTB mRNA ratio in the BRCA1-null UWB1.289 than in the BRCA1 wild-type UWB1.289 + BRCA1 cancer cells, with the ASA-B begetting a 140- to150-fold increase of the PARP2/ACTB mRNA ratio in UWB1.289 cells." (PMID 34440232, 2021). "The aggressive behavior of these cancers may be further promoted by concomitant BRCA1 or BRCA2 mutations, cooperating with Notch signaling towards cancer progression." (PMID 33430387, 2021). "Since the implications of carrying a germline BRCA1/2 PV extend beyond cancer treatment to include risks for other cancers and to family members, individuals with positive tumor results still require appropriate genetic counseling and the option of germline testing." (PMID 33030818, 2021). "GT198 has now emerged out of the shadow of BRCA1 as an ever-important cancer gene." (PMID 34476412, 2021).
cancer (continued). "Although a causative link between TMEJ, Polθ and BRCA-gene reversion mutations still remains to be confirmed, this suggests that the potential for Polθ inhibitors might extend beyond BRCA1 mutant cancers with 53BP1/Shieldin complex defects." (PMID 34140467, 2021). "In this study, the case selection pooled affected probands referred for genetic testing because of personal or family history of cancer according to international standards for BRCA1/2 testing and unaffected carrier relatives of probands referred for presymptomatic targeted testing." (PMID 34356116, 2021). "In addition, consistent with the basal-like feature of Brca1 mutant cancers, G600 cells adapt morphology more like mesenchymal feature compared with Brca1 wild type B477 cells, which display epithelial morphology." (PMID 34815798, 2021). "Germline variants in the HR pathway, comprising at least 10 genes, such as BRCA1, BRCA2, ATM, BARD1, BRIP1, CHEK2, NBS1(NBN), PALB2, RAD51C, and RAD51D, lead to inherited susceptibility to specific types of cancers, including those of the breast, ovaries, prostate, and pancreas." (PMID 35008774, 2021). "Data obtained indicate that BRCA1/BRCA2 gene testing may be considered for postmenopausal patients with BC who have a family history of cancer." (PMID 34287479, 2021). "BRCA1 directly interacts with PR, and ATM mutates frequently in PR-positive cancers." (PMID 33891016, 2021). "In addition, the repurposed cancer types for category L drugs are mostly enriched as the BRCA_OV, which are related to the mutant genes BRCA1 and BRCA2." (PMID 33627666, 2021). "As a rule of thumb, women with BRCA1/2 mutations who have no personal history of cancer (previvors) develop BC or OC around 20 years earlier compared to women who develop sporadic BC or OC." (PMID 34090422, 2021). "In addition, cancer treatment of BRCA mutation carriers has advanced with the development of PARP inhibitors, which take advantage of the loss of BRCA1/2 function in tumors." (PMID 34456966, 2021). "Thus, we evaluated the impact of low versus high BRCA1 mRNA expression on patient survival across these cancer types using publicly available TCGA." (PMID 34611475, 2021). "As a consequence, for men harboring BRCA1/2 PVs, despite the increasing knowledge on gene-specific cancer phenotype differences to guide surveillance programs, there is no consensus on the best follow-up strategy for these individuals, and guidelines diverge based on recommendations." (PMID 34298749, 2021). "Biomarker determination via molecular profile assessment and/or NanoString®-based characterization is ongoing to define specific populations of patients with cancer and BRCA1/2 wild-type gene expression for evidence of further sensitivity or resistance to Vigil." (PMID 34452019, 2021). "Another participant expressed that her own cancer was not BRCA1/2-related and thus not likely to increase risk for her children." (PMID 34711227, 2021). "Mutations of either BRCA1 or BRCA2 increase cancer risk in several different tumor types, including breast and ovarian, highlighting the importance of DSB repair factors in maintaining genome integrity and suppressing human diseases such as cancer." (PMID 34659365, 2021). "Furthermore, neutralization of CCL5 blunted PARPi-driven fibroblast activation and boosted the cancer suppression efficiency of PARPis in BRCA1/2-wild type and BRCA1/2-mutant OC xenograft models." (PMID 34108603, 2021). "Interestingly, the BRCA1 gene showed a significant association, emphasizing that subjects born with CLP are susceptible to cancer and have shorter lifespan." (PMID 34941638, 2021). "Of note, most of our current knowledge of BRCA1 derived from studies using human cancer cell lines." (PMID 34421362, 2021).
cancer (continued). "We demonstrated that aside from BRCA1/2 in well-known BRCA-associated cancer types (breast, ovarian, pancreatic, and prostate), several other HR gene mutations are associated with HRD in a broad range of cancers." (PMID 34572800, 2021). "Blocking PARP proteins with drugs can kill cancer cells with problems in their BRCA1 proteins." (PMID 34142659, 2021). "A patient’s prognosis for BRCA1/2-related cancer depends on the stage at which the cancer is diagnosed and on the type of mutation; however, studies of survival have revealed conflicting information for individuals with germline BRCA1 or BRCA2 pathogenic variants when compared to controls." (PMID 34207450, 2021). "Since OVAR5 and 8 cell lines are considered resistant to PARPis with no reported alterations in any of the DNA repair genes including BRCA1 and 2 (Cancer Cell Line Encyclopedia on the cbioportal.org), we used these cell lines for the PARPi synergy study with QC." (PMID 34572872, 2021). "Pathogenic variants of BRCA1 are created by small insertions or deletions that give rise to a non-functional protein; both alleles of BRCA1 must be mutated and lost for cancer to develop." (PMID 33513753, 2021). "Notably, all carcinomas with acquired platinum resistance (i.e., BRCA reversion mutation and BRCA1 promoter demethylation) remained LOH-high." (PMID 33941784, 2021). "The analysis of the ovarian profile in this subgroup of BRCA1 and 2 as well as cancer patients with no mutation showed the need for a greater amount of gonadotropins to obtain effective stimulation." (PMID 31872386, 2020). "PARP1 inhibitors disturb the single strand repair that causes persistent double strand breaks and lethality in BRCA1-deficient cancers lacking the capacity for HR repair." (PMID 32405340, 2020). "In addition, higher expression of molecules associated with the DNA damage repair pathways such as BRCA1/2, PARP, and γH2AX were associated with shorter survival of human cancer of the breast, ovary, and soft tissue." (PMID 33198792, 2020). "Women with a BRCA1/2 mutation and no previous cancer diagnosis were recruited from the US, Canada, the UK, Australia, and from a national advocacy group." (PMID 33014209, 2020). "In other cancer cells, with wild‐type status of BRCA1/2, metformin causes an increase in NADH levels, but not as much in NAD+." (PMID 32400970, 2020). "Therefore, family history and variant location can be considered jointly with the PRS to predict cancer risks for BRCA1/2 carriers." (PMID 32665703, 2020). "Genetic testing for BRCA1 and BRCA2 pathogenic variants has become an important part of clinical practice for cancer risk assessment and for reducing individual risk of developing cancer." (PMID 33081408, 2020). "LTGC has been shown to occur at Tus/Ter-induced stalled replication forks in BRCA1 deficient cells, and may be responsible for the TD signature commonly observed in BRCA1 mutant cancers." (PMID 32182354, 2020). "Similarly, in other cancer models, BRCA1-KO fibroblasts treated with sera (containing EVs) from cancer patients yielded higher proliferation and malignant transformation than wild type control fibroblasts." (PMID 32485907, 2020). "The difference was even more apparent in “sporadic” OC cases (with no family cancer history), where BRCA1/2 mutations were found in 6 out of 45 (13.3%) women ≥70 years but in none of 52 cases diagnosed at <30 years." (PMID 32295079, 2020).